SMCHD1 (structural maintenance of chromosomes flexible hinge domain containing 1)
Description:
Non-canonical member of the structural maintenance of chromosomes (SMC) protein family that plays a key role in epigenetic silencing by regulating chromatin architecture (By similarity). Promotes heterochromatin formation in both autosomes and chromosome X, probably by mediating the merge of chromatin compartments (By similarity). Plays a key role in chromosome X inactivation in females by promoting the spreading of heterochromatin. Recruited to inactivated chromosome X by Xist RNA and acts by mediating the merge of chromatin compartments: promotes random chromatin interactions that span the boundaries of existing structures, leading to create a compartment-less architecture typical of inactivated chromosome X (By similarity). Required to facilitate Xist RNA spreading (By similarity). Also required for silencing of a subset of clustered autosomal loci in somatic cells, such as the DUX4 locus. Has ATPase activity; may participate in structural manipulation of chromatin in an ATP-dependent manner as part of its role in gene expression regulation. Also plays a role in DNA repair: localizes to sites of DNA double-strand breaks in response to DNA damage to promote the repair of DNA double-strand breaks. Acts by promoting non-homologous end joining (NHEJ) and inhibiting homologous recombination (HR) repair.
Synonyms: KIAA0650; FSHD2; BAMS
Tractability: Small molecule: a structure with a bound ligand is known. PROTAC: UniProt records ubiquitination sites on it; ubiquitination databases record sites on it; its protein half-life has been measured.
Target class: Enzyme; Hydrolase
Gene: Protein-coding gene on chromosome 18 (2,655,668 to 2,805,017, forward strand). Ensembl gene ENSG00000101596.
Subcellular location: Chromosome
Subcellular location (Human Protein Atlas): Nucleoplasm; Nuclear bodies
Gene Ontology:
Molecular function: ATP hydrolysis activity; protein binding; protein homodimerization activity; ATP binding
Biological process: dosage compensation by inactivation of X chromosome; negative regulation of double-strand break repair via homologous recombination; nose development; positive regulation of DNA repair; positive regulation of double-strand break repair via nonhomologous end joining; chromosome organization; double-strand break repair
Cellular component: Barr body; chromosome; chromosome, telomeric region; nuclear body; nucleoplasm; site of double-strand break
Genetic constraint (gnomAD): Loss-of-function variants: 36 observed, 138.82 expected, observed/expected ratio (o/e) 0.26, 90% interval 0.2 to 0.34. The upper end of that interval is the gene's LOEUF score, 0.34, which puts it in group 1 of 6, group 1 being the genes least tolerant of losing a copy. Missense variants: 1,135 observed, 1,566.1 expected, observed/expected ratio (o/e) 0.72, 90% interval 0.69 to 0.76. Synonymous variants: 511 observed, 527.4 expected, observed/expected ratio (o/e) 0.97, 90% interval 0.9 to 1.04.
Gene-disease validity (ClinGen):
ClinGen rates the evidence that SMCHD1 causes each of these diseases.
arhinia, choanal atresia, and microphthalmia (autosomal dominant): Definitive. Any syndromic disease characterized by severe hypoplasia of the nose and eyes, palatal abnormalities, deficient taste and smell, inguinal hernias, hypogonadotropic hypogonadism with cryptorchidism, and normal intelligence that occurs due to variation in the SMCHD1 gene.
Homologues: Orthologues: chimpanzee SMCHD1 (99% identical), macaque SMCHD1 (98% identical), dog SMCHD1 (94% identical), rabbit SMCHD1 (93% identical), pig SMCHD1 (92% identical), guinea pig SMCHD1 (89% identical), rat Smchd1 (88% identical), mouse Smchd1 (87% identical), tropical clawed frog smchd1 (63% identical), zebrafish smchd1 (48% identical).
Diseases named in the same sentence as SMCHD1 in open-access papers:
SMCHD1 is named in the same sentence as 50 diseases in open-access papers, as found by Europe PMC text mining. Sharing a sentence is not in itself a finding about the gene and the disease. The quoted sentences say what the papers report.
facioscapulohumeral muscular dystrophy (17 papers, 2013 to 2026). An autosomal dominant disorder affecting the skeletal muscles of the face, scapula, and upper arm. "Diminished SMCHD1 function in muscle fibers causes Facioscapulohumeral Muscular Dystrophy (FSHD2) through derepression of the D4Z4 chromatin domain, an event which permits the aberrant expression of the disease-causing gene DUX4." (PMID 38994563, 2024). "SMCHD1 is a disease modifier and a causative gene for facioscapulohumeral muscular dystrophy (FSHD) type 1 and type 2, respectively." (PMID 30071896, 2018). "SMCHD1 mutations were also identified as a causal factor in two distinct human disorders, Facioscapulohumeral muscular dystrophy (FSHD) and Bosma arhinia and microphthalmia (BAMS), both of which showed aberrations in genomic structure and epigenetic modifications." (PMID 38976714, 2024). "Facioscapulohumeral muscular dystrophy (FSHD) is in most cases caused by a contraction of the D4Z4 macrosatellite repeat on chromosome 4 (FSHD1) or by mutations in the SMCHD1 or DNMT3B gene (FSHD2)." (PMID 28587678, 2017). "Mutations in SMCHD1 cause facioscapulohumeral muscular dystrophy (FSHD), by overexpressing DUX4 in muscle cells." (PMID 38809976, 2024). "Loss of function mutations in the SMCHD1 gene are observed in a subgroup of patients with the muscle-wasting condition Facioscapulohumeral Muscular Dystrophy (FSHD), one of the most frequent neuromuscular diseases." (PMID 38994563, 2024). "Loss-of-function mutations of SMCHD1 result in DNA hypomethylation of the D4Z4 macrosatellite array on chromosome 4, which underlies the onset of facioscapulohumeral muscular dystrophy, a muscular developmental disease." (PMID 37010434, 2023). "Heterozygous mutations in SMCHD1 are found in two distinct human disorders: loss of function mutations in facioscapulohumeral muscular dystrophy (FSHD), and potentially gain of function mutations in the rare craniofacial disorder Bosma arhinia and microphthalmia (BAMS)." (PMID 33186096, 2020). "Recently, mutations in human SMCHD1 have been shown to underlie type 1 and type 2 facioscapulohumeral muscular dystrophy (FSHD) (8, –, 10), with both types of the disease being dependent on the epigenetic silencing function of SMCHD1 at the D4Z4 repeat sequence." (PMID 26391951, 2015). "The chromosomal protein SMCHD1 plays an important role in epigenetic silencing at diverse loci, including the inactive X chromosome, imprinted genes, and the facioscapulohumeral muscular dystrophy locus." (PMID 26391951, 2015). "Here alternative modes of repression of D4Z4 by SMCHD1 and LRIF1 are identified, relevant for understanding facioscapulohumeral muscular dystrophy." (PMID 37380887, 2023). "Although initial studies of Smchd1 used these two classic models of epigenetic control, it has become clear that Smchd1 has a broader role in regulating gene expression during normal development, in cancer and in the development of facioscapulohumeral muscular dystrophy (FSHD)." (PMID 26981392, 2016).
facioscapulohumeral muscular dystrophy type 2 (13 papers, 2014 to 2025). "Mutations in SMCHD1 are causative for the development of facioscapulohumeral muscular dystrophy type 2." (PMID 39941288, 2025). "Similar SMCHD1 variants have been identified in individuals with type 2 Facioscapulohumeral muscular dystrophy (FSHD2) and in those with Bosma arhinia microphthalmia syndrome (BAMS)." (PMID 39742135, 2024). "In humans, a deletion mutation (K274del) in SmcHD1 located at a conserved residue in the GHKL ATPase domain combined with a permissive 4q35 allele was suggested as a cause for Facioscapulohumeral muscular dystrophy type 2 (FSHD2)." (PMID 24818964, 2014). "Furthermore, SMCHD1 restricts herpesvirus replication by binding viral lytic origins and inhibiting replication complexes; mutations in SMCHD1 cause facioscapulohumeral muscular dystrophy type 2 (FSHD2) through aberrant gene silencing." (PMID 41158309, 2025). "In addition, SMCHD1 mutations are known to cause facioscapulohumeral muscular dystrophy type 2 (FSHD2), particularly when the mutations co-occurred with disease-susceptible alleles at the D4Z4 locus." (PMID 32620854, 2020). "SMCHD1 function is highly relevant to human disease, including BAMS and facioscapulohumeral muscular dystrophy type 2 (FSHD2; MIM158901)." (PMID 38773541, 2024). "Variants in the gene SMCHD1, which encodes an epigenetic repressor, have been linked to both congenital arhinia and a late-onset form of muscular dystrophy called facioscapulohumeral muscular dystrophy type 2 (FSHD2)." (PMID 31312724, 2019). "Each of these three CNVs contained one likely causative disease gene: SMCHD1, PMP22, or MTM1, involved in facioscapulohumeral muscular dystrophy-2 (digenic inheritence with the D4Z4 permissive haplotype), Charcot-Marie-Tooth disease 1A, and X-linked myotubular myopathy, respectively." (PMID 36781956, 2023).
muscular dystrophy (10 papers, 2019 to 2024). Muscular dystrophy (MD) refers to a group of more than 30 genetic diseases characterized by progressive weakness and degeneration of the skeletal muscles that control movement. "Notably, truncation variants of SMCHD1 have been found to be common in FSHD2, a rare, oligogenic form of muscular dystrophy." (PMID 38773541, 2024). "However, given that previous molecular analyses of SMCHD1 primarily focused on individuals with facial anomalies or muscular dystrophy, further studies are needed to clarify the phenotypic variations of SMCHD1 abnormalities." (PMID 32620854, 2020). "SMCHD1 mutations holds a complex relationship with these very different developmental diseases as FSHD individuals do not present facial abnormalities observed in BAMS and BAMS individuals do not display muscular dystrophy." (PMID 31941450, 2020).
Bosma arhinia microphthalmia syndrome (9 papers, 2019 to 2025). "Missense mutations in the SMCHD1 gene impair its gene-silencing capacity and can underlie Bosma arhinia microphthalmia syndrome (BAMS)." (PMID 41158309, 2025). "In the same studies, the authors found that most patients carrying SMCHD1 variants presented a clinical phenotype consistent with Bosma arhinia microphthalmia syndrome (BAMS), characterized by the triad arhinia, ocular defects and CHH." (PMID 34502334, 2021). "Recently, the genetic connection between FSHD2 and arhinia/Bosma arhinia microphthalmia syndrome (BAMS), caused by mutations in the SMCHD1 gene, has led to a wider interest in the epigenetic analyses of the 4q35 locus using these two protocols." (PMID 34441403, 2021). "Previously, SMCHD1 mutations have been associated with autosomal dominant muscular dystrophy and with the Bosma Arhinia and Microphthalmia Syndrome (BAMS), a rare condition characterized by eye and nose abnormalities." (PMID 33937142, 2021). "Recently, heterozygous SMCHD1 mutations were identified in patients with Bosma arhinia microphthalmia syndrome (BAMS), an extremely rare syndrome whose triad is the absence of the nose, microphthalmia, and IHH16–18." (PMID 32620854, 2020). "BAMS (Bosma Arhinia Microphthalmia Syndrome) is characterized by anomalies of the nose, eye defects (high risk of coloboma and cataract) and delayed puberty (hypogonadotropic hypogonadism); this syndrome is caused by the presence of SMCHD1 gene variants on chromosome 18." (PMID 39742135, 2024).
Facioscapulohumeral dystrophy (5 papers, 2013 to 2023). Facioscapulohumeral muscular dystrophy (FSHD) is characterized by progressive muscle weakness with focal involvement of the facial, shoulder and limb muscles. "Structural Maintenance of Chromosomes Hinge Domain Containing 1 (SMCHD1) is a chromatin repressor, which is mutated in > 95% of Facioscapulohumeral dystrophy (FSHD) type 2 cases." (PMID 34880314, 2021). "Facioscapulohumeral dystrophy (FSHD) is commonly associated with contraction of the D4Z4 macro-satellite repeat on chromosome 4q35 (FSHD1) or mutations in the SMCHD1 gene (FSHD2)." (PMID 26446085, 2015).
microphthalmia (3 papers, 2020 to 2024). Congenital or developmental anomaly in which the eyeballs are abnormally small. "SMCHD1 is a causative gene for Bosma arhinia microphthalmia syndrome characterized by arhinia, microphthalmia and IHH." (PMID 32620854, 2020). "Very recently, a rare SMCHD1 variant was also identified in a patient with IHH, combined pituitary hormone deficiency (CPHD) and septo-optic dysplasia (SOD), in the absence of arhinia, microphthalmia or muscle involvement." (PMID 34209568, 2021).
microphthalmia syndrome (3 papers, 2020 to 2024). "To fill this gap, we determined the episignature associated with heterozygous SMCHD1 variants in primary cells and cell lineages derived from induced pluripotent stem cells for Bosma arhinia and microphthalmia syndrome (BAMS) and type 2 facioscapulohumeral dystrophy (FSHD2)." (PMID 37334829, 2023).
bladder cancer (2 papers, 2021 to 2023). "Mutations of SMCHD1 are infrequent in human cancers; however, a recent report defined a model in which somatic alterations of three genes, including SMCHD1, are predictive of overall survival in human bladder cancer." (PMID 37079639, 2023). "A three protein-coding genes prognostic model including SMCHD1 predicts overall survival in bladder cancer patients." (PMID 34260414, 2021).
colon carcinoma (2 papers, 2017 to 2023). "A recent SMCHD1 ChIP-seq study carried out in HCT116 human colon carcinoma cells identified an SMCHD1 binding peak within the region of the tRNA cluster on chromosome 1 at (chr1:161,423,907-161,423,948) (Nowak A, Armenise C, Rey E, Déjardin J GSE46462)." (PMID 28587678, 2017).
lymphoma (2 papers, 2015 to 2016). A malignant (clonal) proliferation of B- lymphocytes or T- lymphocytes which involves the lymph nodes, bone marrow and/or extranodal sites. "To elucidate its role in transcriptional regulation, we performed two independent genome-wide RNA-sequencing studies comparing wild-type and Smchd1 null samples in neural stem cells and lymphoma cell lines." (PMID 26981392, 2016). "In this second example, we analyse data from an RNA-seq experiment that aimed to identify genes that are transcriptionally regulated by Smchd1 in lymphoma cell lines." (PMID 25925576, 2015). "Genes uncovered in the Lymphoma analysis are consistent with previous reports in a different system that profiled male embryos, where the expression of imprinted genes such as Peg12 and Mkrn3 was shown to be disturbed in the absence of Smchd1." (PMID 26981392, 2016).
neuroblastoma (2 papers, 2014 to 2020). Neuroblastoma (NB) is the most common solid, extracranial childhood tumor. "In a more relevant cellular model, SH-SY5Y neuroblastoma cells, knock-down of SmcHD1 displayed dysregulation of BWS and SRS associated genes." (PMID 24818964, 2014). "In addition, we demonstrated that in SH-SY5Y neuroblastoma cells, SMCHD1 regulates expression of imprinted genes associated with two imprinting disorders, Beckwith-Wiedemann and Silver-Russell syndromes (BWS, SRS)." (PMID 31941450, 2020). "We tested knock-down of SmcHD1 in a more relevant cell line SH-SY5Y cells, a neuroblastoma derived cell line." (PMID 24818964, 2014). "Therefore, we profiled SMCHD1 genome wide occupancy in human neuroblastoma SH-SY5Y cells and evaluated if DNA methylation is required for SMCHD1 genomic binding by treating cells with the DNA demethylating reagent, 5-azacytidine (5-azaC)." (PMID 31941450, 2020). "Thus, to investigate DNA methylation dependency of SMCHD1 in regulating gene expression, we sought to compare SMCHD1 genomic localization in SH-SY5Y neuroblastoma cells cultured under normal conditions and those treated with 5-azaC to induce global loss of DNA methylation." (PMID 31941450, 2020). "Consistent with a previous study in murine neuronal stem (NSC) cells which showed that SMCHD1 occupancy is not restricted to gene promoters, we found that SMCHD1 more actively binds to introns and intergenic regions in a 5-azaC sensitive manner in human neuroblastoma SH-SY5Y cells." (PMID 31941450, 2020).
Prader-Willi syndrome (2 papers, 2013 to 2014). "Identification of genes associated with BWS and SRS extends our understanding of the role of SmcHD1 in regulating imprinted clusters beyond that associated with Prader-Willi syndrome (PWS) and Angelman syndrome (AS)." (PMID 24818964, 2014). "Additionally, we found that Smchd1 is required for CpG island methylation and silencing at a cluster of four imprinted genes in the Prader-Willi syndrome (PWS) locus on chromosome 7 and genes from the protocadherin-alpha and -beta clusters." (PMID 23754746, 2013).
Silver-Russell syndrome (2 papers, 2014 to 2020). Silver-Russell syndrome is characterized by growth retardation with antenatal onset, characteristic facies and limb asymmetry. "We confirm that SmcHD1 can repress genes in the protocadherin β gene cluster and extends its targets to a gene cluster with parent-of-origin imprinting associated with Beckwith-Wiedemann/Silver-Russell syndromes (BWS/SRS, respectively)." (PMID 24818964, 2014).
herpesvirus infection (1 paper, 2023). "SMCHD1 is a well-characterized epigenetic regulator that plays a critical role in development, but its function in herpesvirus infection remains unknown." (PMID 37010434, 2023). "The characterization of SMCHD1 as a pan-herpesvirus restriction factor deepens our understanding of the arms race between herpesviruses and host, which could be harnessed to develop new therapeutics for the treatment of herpesvirus infection and related diseases." (PMID 37010434, 2023).
latent infection (1 paper, 2023). "Next, we wondered whether SMCHD1 affected KSHV latent infection." (PMID 37010434, 2023).
lentivirus infection (1 paper, 2024). Virus diseases caused by the Lentivirus genus. "Using three different shRNAs targeting distinct regions of the SMCHD1 transcript, we observed a reduction in mRNA and protein accumulation that varied between 50 and 90% when examined 5 days after lentivirus infection." (PMID 38994563, 2024).
myotonic dystrophy type 2 (1 paper, 2019). Myotonic dystrophy type 2 (MD2), also known as proximal myotonic myopathy, is a very rare genetic multi-system disorder of late childhood or adult-onset characterized by mild myotonia, muscle weakness, and rarely cardiac conduction disorders. "All patients were genetically tested for FSHD1, nine were tested for myotonic dystrophy type 2 (DM2), and in seven patients, the D4Z4 methylation was assessed, with subsequent sequencing of SMCHD1 when appropriate." (PMID 31471688, 2019).
prostate carcinoma (1 paper, 2020). A carcinoma that arises from epithelial cells of the prostate gland. "One study suggested that SMCHD1 may be a candidate tumor suppressor gene in prostate cancer." (PMID 33150179, 2020).
Sepsis (1 paper, 2025). Sepsis is defined as life-threatening organ dysfunction caused by a dysregulated host response to infection. "Notably, six of these genes, including GSPT2, SMCHD1, SF3B1, DDX3X, and F3, showed significant differences and consistent trends between sepsis and septic ARDS samples in the GSE66890 and GSE32707 databases." (PMID 39854144, 2025).
tumor (7 papers, 2013 to 2024). "Recently, Smchd1 has been shown to act as a tumor suppressor and mutations in SMCHD1 have been shown to be tightly associated with the human disease facioscapulohumeral dystrophy type 2 (FSHD2)." (PMID 24025402, 2013). "The significant genes observed were PYHIN1, IKZF1, CASP8, DAPK1 and SMCHD1 expression in tumor samples." (PMID 30867653, 2019). "However, there has been comparatively little research into the role of SMCHD1 in different cancer types, so whether it functions as a tumor suppressor or an oncogene is not yet clear." (PMID 33150179, 2020). "Patients #5, #6, and #7 (without tumor samples) showed an overlap of four genes (SORL1, PTPRC, MIR6819, and NAMPT), while #6 and #7 also shared five genes (CELF2, EDEM3, SMCHD1, RAVER1, and CXCR1)." (PMID 39001407, 2024).